PMS2 (PMS1 homolog 2, mismatch repair system component)
Diseases named in the same sentence as PMS2 in open-access papers (continued):
Sharing a sentence is not in itself a finding about the gene and the disease.
tumor (continued). "Typically, these cases would show loss of MLH1 and PMS2 in tumor nuclei, as biallelic inactivation of MLH1 would result in loss of MLH1 and its dimerization partner PMS2." (PMID 38344144, 2023). "The tumor showed a somatic MSH6 mutation (MSH6 c.3261del p.Phe1088Serfs*2) and was positive for MLH1 methylation accounting for the loss of MLH1/PMS2." (PMID 37101184, 2023). "Poor tumor differentiation and MLH1/PMS2 heterodimer deficiency have been identified as potential predictors for CDX2 expression loss." (PMID 37325467, 2023). "The MMR status was known for 40 tumors, of which 34 (85%) were MMR-proficient and 6 (15%) were MMR-deficient with MLH1/PMS2 loss of staining and positive BRAF mutation, which associates with a sporadic tumor." (PMID 36203446, 2022). "The analysis of the primary tumor with 80% of tumor cells showed a loss of MLH1 and PMS2 (dMMR) with MSI status and a BRAFV600E mutation." (PMID 35457245, 2022). "The result showed excellent agreement in 98.1% of cases between MSI-NGS and MMR-IHC analyses with one tumor described MSS by NGS but loss of MLH1 and PMS2 expression by IHC." (PMID 36003784, 2022). "The index case whose CRC tumor showed MSI with loss of expression of MLH1 and PMS2 proteins, underwent total colectomy." (PMID 36454741, 2022). "The mutational profile of the index patients’ tumor also showed a high contribution of signature SBS26 (38%), which was recently found to be specific for PMS2 deficiency." (PMID 36291559, 2022). "This latter tumor showed partly clonal loss of MLH1 and PMS2 staining and partly retained MMR staining in tumor biopsies." (PMID 35877698, 2022). "His tumor showed loss of MLH1 and PMS2 proteins in IHC and displayed microsatellite instability (MSI-H)." (PMID 36454741, 2022). "In the “p” portion, nuclear staining of four proteins was apparent, whereas in the “d” portion, nuclear staining of two proteins (MLH1 and PMS2) was lost in tumor cells." (PMID 35596629, 2022). "Among the four MLH1-mutant tumors, complete loss of both MLH1 and PMS2 IHC in the tumor cells was present in three cases (Patient #1, 9, and 10), but one case showed complete loss of MLH1 and heterogeneous loss of the partner protein PMS2 (Patient #11)." (PMID 34848827, 2022).
tumor (continued). "Case 27 is a CRC sample with 50% tumor cells with combined loss of MLH1 and PMS2 expression and concordant true positive results in all three molecular assays." (PMID 34145315, 2021). "Immunohistochemical staining was carried out to assess the expression of MLH1 and PMS2 protein in tumour tissue." (PMID 34925852, 2021). "The greatest histomorphological group of tumors were SNSCCs with 125 samples, and four (3.2%) showed a loss of PMS2 expression and at least a significantly reduced or complete loss of MLH1 expression in tumor cells." (PMID 34885191, 2021). "The tumor of patient 6 showed a complete loss of MLH1 and PMS2 staining and was therefore classified into the MSI group." (PMID 33467460, 2021). "One case was classified as an MSI tumor based on the simultaneous loss of the MLH1 and PMS2 protein expression detected by MMR IH." (PMID 33335133, 2020). "Next Generation Sequencing (NGS) analysis identified PMS2 mutations (germline in one tumour and somatic in the other) as the primary event and somatic MSH6 mutation as the secondary event in both tumours." (PMID 32664968, 2020). "PMS2 is one of the mismatch repair (MMR) genes, which causes genetic instability and is associated with tumour progression." (PMID 31391089, 2019). "In the case of PMS2 and BMPR1A variants, the former appears to be penetrant on the basis of tumor studies, whereas the significance of the latter is unclear." (PMID 29909963, 2018). "The tumor carried a KRAS mutation, and MLH-1, MSH-2, MSH-6, and PMS-2 immunostaining results were normal, suggesting microsatellite stability." (PMID 30043132, 2018). "A mismatch repair panel revealed a mismatch repair protein deficient tumor with loss of MLH1 and PMS2 expression." (PMID 28840050, 2017).
tumor (continued). "Patient I:47 has a tumor which is MSI-H and present a loss of MLH1/PMS2 proteins, this patient has a VUS in MLH3, c.1870G > C, p.Glu624Gln." (PMID 27696107, 2017). "Immunohistochemistry was repeated on ovarian tissue; 0% tumour positivity and 0% control positivity for PMS2 was established." (PMID 28381238, 2017). "Sporadic tumour development is likely more common with the lower penetrance mutations in MSH6 and PMS2." (PMID 28466842, 2017). "This delayed diagnosis until subsequent IHC analysis of the ovarian tumour, which established 0% immunopositivity for PMS2 in tumour tissue and control tissue." (PMID 28381238, 2017). "Tumour block 3c showed retained MLH1 and PMS2 expression, whereas tumour block 3a and 3b showed subclonal (15%) and complete loss of MLH1 and PMS2 expression, respectively." (PMID 28424422, 2017). "Immuno-histochemical staining demonstrating MLH1 and PMS2 expression of tumor cells is strong and diffuse immune-reactivity." (PMID 28903413, 2017). "Tumor-derived DNA methylation at five probes across the gene body region of PMS2 was significantly decreased (Δβ 25.70%; adj." (PMID 27902704, 2016). "In summary, this is the first report that shows PMS2 to display a protection against PCa by inhibiting cell proliferation, migration, and invasion in vitro as well as tumor growth in vivo." (PMID 26036629, 2015). "To validate the suppressive effect of PMS2 under in vitro conditions, we also determined effects of PMS2 on tumor growth in animal models." (PMID 26036629, 2015). "We observed that expression of PMS2 inhibited DU145 cell tumor formation throughout the duration which lasted 5 weeks whereas tumors grew rapidly and were visible in pCMV animals (P < 0.05)." (PMID 26036629, 2015). "In prostate tissue, PMS2 has been shown to be downregulated in tumor regions as compared to normal areas and benign hyperplasia." (PMID 26036629, 2015). "Nuclear PMS2 expression was seen in all tumours and the median expression H score was 155 (range 20-250) (Figure 5B5)." (PMID 25026297, 2014). "Concurrent screening for the BRAF V600E mutation in tumour DNA from MSI positive cases exhibiting loss of MLH1 and PMS2 expression by IHC, will further assist in the exclusion of non-eligible patients." (PMID 25133505, 2014).
tumor (continued). "There was normal staining for PMS2 in 15/18 (83.3%) of tumours included in the AMS1/AMS2/Bethesda criteria." (PMID 24790682, 2014). "Of tumours included in AMS1/AMS2/Bethesda criteria 15/18 (83.3%) showed normal staining for PMS2 with IHC." (PMID 24790682, 2014). "In recurrent GBM tumours, the expression of MLH1 and PMS2 was reduced when compared to primary tumours." (PMID 24259277, 2013). "In order to obtain a more uniform group of sporadic BAN samples for further investigation, we excluded all seven patients whose tumours were MSI and an additional patient (age, 51 years) whose tumour showed loss of PMS2 protein expression." (PMID 23286373, 2013). "This case was a 49-year-old male with an MSI tumor in the cecum that showed loss of MLH1 and PMS2 protein expression." (PMID 23049789, 2012). "The down-regulation of MLH1 and PMS2 observed in these experiments is comparable to previous work conducted on different murine tumour cell lines grown as spheroids." (PMID 22145025, 2011). "We also demonstrated a strong synergistic anti-tumor activity at lower doses of the PMS2 plasmid and cisplatin in HeLa cells by CI analysis." (PMID 20178594, 2010). "We demonstrated a strong synergistic anti-tumor activity at the lower doses of the PMS2 plasmid (2-4 μg/ml) and cisplatin (4-10 μg/ml) in HeLa cells by CI." (PMID 20178594, 2010). "To understand the mechanistic contributions of MLH3 and PMS2 in gastrointestinal tumor suppression, we generated Mlh3−/−;Apc1638N and Mlh3−/−;Pms2−/−;Apc1638N (MPA) mice." (PMID 18551179, 2008). "Because Mlh3;Pms2 deficiency also increased gastrointestinal tumor progression, we used array-CGH to identify a recurrent tumor amplicon." (PMID 18551179, 2008). "Note: If IHC reveals that the tumor has the BRAF V600E variant in cases with MSI-H or loss of expression of both MLH1 and PMS2 proteins, a sporadic tumor is likely and there is no need to proceed to genetic testing (STEP 3)." (PMID 41214301, 2026). "In multivariate logistic regression analysis, BRAFV600E (HR=5.983, 95% CI: 2.075-17.251, p=0.001) and tumor size > 5 cm (HR=1.989, 95% CI: 1.017-3.889, p=0.045) were independent risk factors for absent PMS2 expression." (PMID 40458404, 2025). "For those without germline MMR pathogenic variant, tumour-based testing to identify biallelic somatic MLH1 mutations would provide a definitive diagnosis for an important proportion of MLH1/PMS2-deficient cases." (PMID 40208414, 2025). "The TMB of patients with variants in the other three MMR genes was greater than that of patients with PMS2 variants in the total population and in the non-CNS LS-related tumor group." (PMID 41261115, 2025).
tumor (continued). "This may be due to the higher mortality rate of tumor cells after colonization of tumor cells overexpressing PMS2 in the mouse brain." (PMID 38714954, 2024). "In Case 3, which had the lowest tumour content (10–15%), a PMS2 mutation was found suggesting that the lack of KRAS mutation in this sample is a genuine finding." (PMID 38762572, 2024). "RNA sequencing was performed on tumor cells in PMS2 amplification and control groups." (PMID 38714954, 2024). "It is reasonable to hypothesize that PMS2 amplification occurs in tumor cells after entering the brain tissue through blood circulation, enabling better adaptation to the brain microenvironment." (PMID 38714954, 2024). "We confirmed that expression level of PMS2 was elevated in PMS2 amplificated tumor cells." (PMID 38714954, 2024). "We hypothesized that by using a higher threshold, we could account for positive internal controls (non-tumour cells expressing PMS2 or MSH6) that were erroneously classified as true positives." (PMID 39040241, 2024). "This is consistent with the absence of PMS2-related early-onset CRC, detected by surveillance colonoscopy, also suggesting that the dMMR crypt foci do not contribute to PMS2-deficient tumor development." (PMID 38473212, 2024). "However, within MLH1/PMS2 deficient cancers, CRC showed higher TMB than endometrial cancer and other tumor histologies." (PMID 38966168, 2024). "As a result, we consider loss of MLH1 transcription as causative for the absence of the MutLA complex (MLH1/PMS2) and the consequently observed dMMR, microsatellite instability, high tumor mutational burden, and mutational profile." (PMID 38504345, 2024). "Comparisons of the mutational landscape of CSF samples with that of plasma revealed that PMS2 gene mutations in tumor cells are identified in a copy-number amplified form in the cerebrospinal fluid, no mutations in the PMS2 gene were detected in the plasma." (PMID 38714954, 2024). "Loss of expression of PMS2 protein was observed in both tumor and non-neoplastic cells for all the 7 patients with a biallelic germline PMS2 mutation." (PMID 39233831, 2024). "Genes with fewer than 10 tumor variants identified (MLH1, PALB2, PMS2) had more variable frequencies of being germline (likely due to low n value for each of these genes), but collectively they had a similar percentage of being germline when combined as a single group (40%)." (PMID 36261688, 2023). "From a total of 6830 tumor samples from 6527 individual patients that underwent tumor DNA sequencing, 584 unique tumor variants were identified in the gene list of interest (ATM, BRCA1, BRCA2, MLH1, MSH1, MSH6, PALB2 and PMS2) from 503 unique tumor samples/patients during the study period." (PMID 36261688, 2023). "Loss of PMS2 expression was seen in tumor tissue, while PMS2 expression in non-neoplastic cells was retained." (PMID 37308967, 2023). "In tumor material of the 2nd relapse, PMS2 expression was retained, and MSI was low." (PMID 37308967, 2023).